CD44 (CD44 molecule (IN blood group))
Diseases named in the same sentence as CD44 in open-access papers (continued):
Sharing a sentence is not in itself a finding about the gene and the disease.
tumor (continued). "In vitro and in vivo tests showed that small interfering RNA targeting CD44 in combination with paclitaxel delivered via a cancer-targeted delivery system resulted in the induction of cell death and reduced the tumour." (PMID 38201468, 2023). "Our computer-based analysis revealed that the messenger (m)RNA levels of VEGFA, CTNNB1, MMP7, and CD44 oncogenic signatures were upregulated in tumor samples compared to normal samples of patients with CRC tissues, with significant p values (<0.05)." (PMID 36672201, 2023). "Accordingly, α-SMA levels and tumor-promoting capacity of BM-MSCs enhanced by CD44-enriched AGS-sEV were obviously eliminated by U0126 and GW9662." (PMID 37158903, 2023). "Besides, CD44 was positively associated with several metabolic pathways, including glycogen biosynthesis, galactose metabolism, glycosaminoglycan biosynthesis, N-glycan biosynthesis, and starch and suctose metabolism, indicating a highly activated tumor microenvironment." (PMID 36776876, 2023). "CD44 expression was detected in 33% (28/86) of patients, both in tumor cells and the surrounding stroma." (PMID 36768723, 2023). "Hyaluronic acid (HA) was included in liposome formulation to increase the targetability of breast cancer tumours since HA binds to CD44, which is overexpressed in tumour cells." (PMID 36771161, 2023). "Using differential gene analysis between the cell states, we found that CD44 can be used to distinguish SPC-high cells from Hmga2-high cells in 7 days KPY tumor organoids." (PMID 36993454, 2023). "An analysis of CD44 isoforms in 254 tumour samples obtained from The Cancer Genome Atlas RNAseqV2 demonstrated that patients with a high expression of the CD44v8-10 isoform have longer survival." (PMID 38201468, 2023). "In particular, cells expressing CD44 showed elevated levels of local tumor formation, correlated with aggressive metastatic behavior." (PMID 36982699, 2023). "CSCs, a subpopulation of cells, are characterized by some key markers, such as CD133, CD166, CD44, CD24, SOX2, OCT4, and ALDH, which are associated with tumor initiation, growth, and therapy resistance." (PMID 36827121, 2023). "Although NK cells invade the tumor enriched with CD44+CD24low/- BCSC, their activity is impaired due to altered expression of ligands on BCSC." (PMID 37445860, 2023). "These demonstrated that CD24, CD45RB, and CD44 had relatively strong changes across all tumor types, rendering them the preferred candidates for panel inclusion." (PMID 37600768, 2023). "Sponge lentivirus for miR-637 knockdown increased the proportion of CD44+CD133+ GSCs in GBM tumor-bearing mice." (PMID 36755314, 2023). "CD44 is a multifunctional protein involved in cell adhesion, cell-matrix adhesion, cell migration, leukocyte homing and activation, tumor invasion, and metastasis." (PMID 37110670, 2023). "The ubiquitous transmembrane cell surface molecule CD44 is widely distributed in normal adult tissue, but is also highly expressed in many tumour cells." (PMID 37662913, 2023). "Paclitaxel dose: 2.5 mg/kg.(+) Decrease in the invasiveness of malignant cells after CD44 suppression(+) Almost complete tumor eradication after 28 days." (PMID 37287910, 2023). "CD44 and its isoforms have clinicopathological effects that promote tumorigenesis and help cancer stem cells maintain their stemness during tumour regeneration after therapy." (PMID 37176928, 2023). "Many studies in recent years have identified the role of CD44 in a subpopulation of tumor cells with self-renewal capacity, the so-called CSCs." (PMID 37328876, 2023). "In our study, we sought to investigate the role of CD44 in the regulation of tumor cell immune evasion and immune cell infiltration, as well as provide novel clues for administering immunotherapy to BLCA patients." (PMID 37316699, 2023). "In MCF7, but not in T-47D cells, 10H10 attenuated the NET-induced expression of CD44, a marker of tumor stemness." (PMID 38201433, 2023).
tumor (continued). "Both MSN and CD44 function in a context-dependent fashion, and their interactions in the extracellular domain are considered necessary for their anti-tumor action." (PMID 37056934, 2023). "The addition of HA, a well-known ligand for the cell surface receptor CD44, which is highly expressed in tumors, enables specific target delivery and enhanced endocytosis of the composite into tumor cells." (PMID 36987269, 2023). "In this study, TIMER was used to investigate the relationship between CD44 expression, and immune cell infiltration into the tumor in BLCA." (PMID 37316699, 2023). "As a single-chain transmembrane glycoprotein, CD44 is widely involved in biological processes, such as cell interaction, adhesion, hematopoietic and tumor metastasis." (PMID 38254942, 2023). "HCT116 cells cocultured with CRC patient’s tumor tissues derived ID1KD TAMs expressed lower levels of CD44 and LGR5 than those cocultured with Ctrl TAMs." (PMID 37996458, 2023). "Conflictingly, CD44 positivity was found to decrease linearly with increasing cancer cell differentiation, leading to an increased Tumor Budding Activity (TBA) and a smaller Cell Nest Size (CNS), two key features driving the EMT process." (PMID 38170015, 2023). "The interaction of tumor cells and monocytes in tissues involves surface molecules such as CD44, which are required to produce reactive oxygen intermediates (ROI)." (PMID 37107200, 2023). "There is a strong relationship between CD44 and EMT in CRC, which is defined by the loss of epithelial markers such as E-cadherin and the acquisition of mesenchymal features in tumour cells." (PMID 37012965, 2023). "Upregulation of CD44 protein expression in HNSCC tumor samples (median: 0.003) compared with normal subjects (median: –1.3); statistically significant (p = 0.0008)." (PMID 37593530, 2023). "Using the Kruskal–Walls test to compare data, we found that overexpression of VEGFA, CTNNB1, MMP7, and CD44 genes promoted primary tumor and cancer metastasis in CRC tissues." (PMID 36672201, 2023). "CD44 is a highly expressed surface protein in solid tumours, while P-selectin is a tumour vasculature biomarker." (PMID 37176928, 2023). "In conclusion, we developed a CD44 and SR-B1 receptors dual-targeting lipid nanoparticle loaded with melittin, which effectively inhibited primary tumor growth and SLN metastasis." (PMID 37528426, 2023). "Liu and co-workers proposed an electrochemical cytosensor to detect HeLa cells based on the overexpression of CD44 in these tumor cells." (PMID 37754116, 2023). "After ingesting by tumor cells via CD44 mediated endocytosis, the acidic lysosomal condition will further trigger the protonation of TA molecules, finally leading to the Fe3+ release of nanoprobe." (PMID 36597067, 2023). "The acquired antifouling biosensor has great efficacy for CD44 analysis with a linear range of 0.5 ng mL−1 to 500 ng mL−1 and is capable of highly sensitive and selective screening of CD44 and CD44-positive tumor cells in heterogeneous liquids." (PMID 36832187, 2023). "Overexpression of the NUMB gene (NUMB endocytic adaptor protein) in CD44-positive cancer stem cells inhibited invasiveness and clonal formation capabilities leading to tumor growth and metastasis inhibition." (PMID 37461792, 2023). "The accumulated HCeC entered into tumor cells by endocytosis mediated by CD44, a targeted receptor of HA overexpressed on most of the malignant tumors, resulting in a promoted PSs cellular uptake." (PMID 37007107, 2023). "Accordingly, numerous NF2 mutations in cancer patients are predicted to perturb the interaction of Merlin with CD44 and anticipated to interfere with the tumor suppressor activity of Merlin." (PMID 37174657, 2023). "In an ICB-treated validation cohort, CD44 levels in the tumour compartment predicted PFS upon multivariate analysis after adjusting for performance status, baseline liver metastasis and LIPI score (HR 0.62, 95%CI 0.40–0.96 and p = 0.035)." (PMID 37835491, 2023).
tumor (continued). "CD44 is a marker for cancer cell migration and is involved in the extravasation of tumor cells into the bloodstream." (PMID 36979915, 2023). "CD44 has been known as a marker of tumor-initiating cells, and plays pro-tumorigenic functions in many cancers." (PMID 36975491, 2023). "The identification of CSC surface markers such as EpCAM, CD44, and CD133 has caused the identification of specific therapeutic targets for inhibiting tumor recurrence and metastasis." (PMID 36810098, 2023). "Prior research reported that the overexpression of CD44 in cancer cells is widely accepted as a marker of higher tumor-initiating potential and invasiveness of cancer cells." (PMID 37117249, 2023). "While in PDAC, WD repeat domain 5 (WDR5), a histone methyltransferase, mediates H3K4me3 on promoters of OPN and CD44 and enhances their expression to promote PD-L1 expression in tumor cells and MDSCs." (PMID 36906534, 2023). "CD44 has been shown to promote tumor growth and invasiveness by recruiting Ezrin to its cytoplasmic tail and thus producing links to the cytoskeleton." (PMID 37371090, 2023). "All tumour models were characteristically “cold” tumours, but after US+CA+aPD-1 treatment they observed significantly (p < 0.05) more CD44+CD8+ cells and the presence of T cell effector functions compared to monotherapies." (PMID 37631324, 2023). "We observed a significant increase in the frequency of the effector like CXCR6+CD44+ cluster in the tumor from Arid2-deleted CD8+ T cell recipients compared with the control (26.2% versus 8.72%)." (PMID 37330910, 2023). "Previous studies revealed that glycoproteins such as CD44 were aberrantly expressed in cancer cells and act as ligands for selectins to facilitate tumor metastasis." (PMID 37031242, 2023). "Specifically, we found that GSCs expressing high cluster of differentiation (CD) 44, which were established by the primary culture of tumor cells obtained from the tumor periphery of highly CD44-expressing GBM patients, can present a high invasive feature." (PMID 37760811, 2023). "We identified that CDK1 activates STAT3 to regulate tumor sphere formation and the expression of stemness-related genes CD44 and SOX2, as well as both CDK1 and STAT3, which are negatively correlated with the prognosis of PDAC patients." (PMID 37743465, 2023). "We found that high CD44 expression of tumor cell expressed significantly higher levels of PD-L1 expression compared to low CD44 expression." (PMID 37316699, 2023). "Interaction of cell surface glycoprotein CD44 with hyaluronic acid (HA) mediates cell adhesion, motility, metastasis, inflammatory responses and tumor development." (PMID 36768572, 2023). "Generally, CD44 is widely expressed on vertebrate cells, and its ability to regulate tumor progression, metastasis, and disease prognosis has been extensively explored." (PMID 36918848, 2023). "We describe the signaling pathways and their regulation in which CD44 transduces intracellular and extracellular molecules to promote tumor proliferation." (PMID 37835592, 2023). "In contrast, both CD44 expression in the tumor periphery and P/C ratio were significantly higher in HI-type GBM than in LI-type GBM." (PMID 37760811, 2023). "Tumor cells isolated from Id1Lyz-KO group expressed lower CD44 and Lgr5 (CSC marker) than those from Id1f/f group." (PMID 37996458, 2023). "This suggests the importance of CD44 expression at the invasive tumor front in early OSCC and its relation with tumor invasion and regional metastasis." (PMID 37593530, 2023). "Previously, it was noted that after undergoing EMT and acquiring a mesenchymal state, breast carcinoma cells actively expressed CSC marker CD44, and tumour sphere formation was also greatly enhanced." (PMID 37108193, 2023). "HA is also internalized into cells through binding to CD44; this property has been exploited for delivery to CD44-overexpressing tumor cells." (PMID 36839922, 2023).
tumor (continued). "Our studies demonstrated that GBM with higher expression of CD44 in the tumor periphery than in the core correlated well with the highly invasive-type GBM as defined on magnetic resonance imaging (MRI), associated with poorer survival of patients." (PMID 37760811, 2023). "The addition of separate αvβ3 integrin and CD44-specific antibodies greatly limited the migration and invasion ability of tumor cells." (PMID 37188183, 2023). "In the present study, the expression of Thbs1, Tnfs, and Cd44 was down-regulated, indicating the potential tumor suppression function of the PEP1 peptide." (PMID 37446885, 2023). "Hyaluronan or hyaluronic acid (HA) is a component of the extracellular matrix that augments tumor proliferation via binding of tumor cell surface receptors including CD44 and receptor for hyaluronan-mediated motility (RHAMM)." (PMID 37513708, 2023). "Some of these adhesion molecules involved in either weak or strong adhesion between tumor cells and endothelium, such as CD44, VCAM1, and VLA4, play indispensable roles in metastasis." (PMID 37108248, 2023). "The dissimilar behavior of the tumor cells also became evident in regard to CD44 alterations (right)." (PMID 37835543, 2023). "The infiltration of CD4 and CD8 T cells, as well as the levels of the TEX marker genes (HAVCR2, TIGIT, CTLA4, LAG3, and PD1) and tumor stem cell marker genes (CD44 and PROM1), were all greater in tissue samples with high TEXSRGs-score." (PMID 37957420, 2023). "Small interfering RNA or blocking antibodies can also disrupt CD44–HA interaction, exhibiting antitumor potency in animal models and even preventing tumor recurrence." (PMID 37107200, 2023). "CD44 is a multifunctional type I transmembrane glycoprotein that mediates metastasis and drug resistance in tumor cells." (PMID 37504249, 2023). "HNSCC cell lines and tumor-derived cells exhibit different stem cell subpopulations based on the presence of CD44, CD24, and ALDH markers." (PMID 37453969, 2023). "CD44 participates in numerous physiological processes, and its dysregulation and aberrant expression correlate to tumor initiation and progression." (PMID 37886001, 2023). "CD44 is the major receptor for hyaluronan and it contributes to cell–matrix interactions, cell migration, and regulation of tumor growth." (PMID 37190507, 2023). "In keeping with that, the markers for anti-tumor immunity, including CD44 and CD8A were significantly reduced in the CDC20-high group." (PMID 37528490, 2023). "In our study, we have observed the presence of CD44‐positive stem cells in the untreated KPC tumours, which is greatly reduced in the Sel‐GemPac‐treated tumours." (PMID 38131168, 2023). "CD44hiCD62Llo T effector cells (hereafter TEF cells) and CD44+CD62Lhi central memory T-like cells (TCM-like cells) from tumor-bearing Shp2f/fLysMCre mice had increased expression of IFN-γ, indicating a state of activation and effector function." (PMID 36581713, 2023). "The results showed higher expression levels of both genes in CD44+c-Myc+EpCAM+ cells, indicating that CSCs were more resistant to gemcitabine with tumor development." (PMID 37553567, 2023). "Notch1 overexpressing PDAC cells had a higher potential to form tumour spheres with an elevated expression of CSC markers CD44 and EpCam." (PMID 37108193, 2023). "Secreted OPN form tumor cells contributes to the accumulation of MDSCs via targeting CD44 and stimulating downstream ERK/MAPK pathway to induce extramedullary myelopoiesis and immune escape." (PMID 36906534, 2023). "GSCs obtained from the primary culture of tumor tissues in GBM expressing high CD44 showed that the expression of CD44v5 was the highest, followed by CD44v6, whereas differentiated GBM cells showed higher expression of CD44v6, followed by CD44v5." (PMID 37835592, 2023). "The interaction between CD44 and HA has been shown to trigger cytoskeletal remodeling and cell signaling changes in the tumor cell, promoting epithelial-mesenchymal transition mechanisms (EMT)." (PMID 37511533, 2023).
tumor (continued). "In this study, we determined CD44 mRNA expression in normal and in tumor tissues for BLCA via the use of the TIMER database." (PMID 37316699, 2023). "They found that mesenchymal CTCs express significantly higher CD44, Vimentin, Nanog and Oct4, and induce more lymph node metastases and a larger tumor size." (PMID 36768876, 2023). "AOT expressed ALDH1, CD44, c-Myc, and Nestin, mainly in epithelial cells of tumor nests and rosette-like structures." (PMID 37761874, 2023). "Next, CD44 + MKN45 cells transfected with sh-NC or sh-CXCR4 were injected subcutaneously or into the tail vein of nude mice to observe tumor growth and liver metastasis." (PMID 37679408, 2023). "As described in the “CD44-promoted tumor proliferation in GBM (GSCs)” section, OPN can activate γ-secretase by binding to CD44." (PMID 37835592, 2023). "For example, P-selectin binds to CD44 molecules, which are expressed on the surface of tumor cells, and PLTMNPs have been shown to target and accumulate in tumor tissues." (PMID 37128288, 2023). "CD44 plays a key role in mediating cell-to-cell and cell-to-matrix interaction, which further helps to maintain the integrity of tissue and also inhibits tumor metastasis." (PMID 37461792, 2023). "Significant correlations were found between the expressions of CD133 and CD44 and more outstanding tumor grades, fibrosis stages, and inflammatory activity." (PMID 37880659, 2023). "Different CSC properties such as self‐renewability, tumor initiation, metastasis, and chemoradioresistance are regulated by CD44, primarily CD44 variable isoforms (CD44v)." (PMID 36289579, 2023). "The mice that received CD44-neg cells had a significantly higher tumor burden than CD44-high cell recipient mice." (PMID 36993454, 2023). "They identified CD44 on tumor cells as a negative regulator of intracellular immune killing via inhibition of CIC formation." (PMID 37790755, 2023). "NEs can bind to circulating tumor cells or inflammatory endothelial cells through ligand receptor interactions, such as CD44 and L-selectin, LFA-1 and ICAM-1, and β 1 integrin and VCAM-1." (PMID 37128288, 2023). "The functionalization of the AuNFs with hyaluronic acid (HA), loaded with DOX in the mesopores, was used to specifically target overexpressed CD44 on tumor cells (MDA‐MB‐231)." (PMID 36683237, 2023). "As most of the CD8+ T cells in tumor-experienced brains were CD44+ memory T cells, while the CD8+ T cells in peripheral tissue were not, we then compared the antitumor effect of CD44+CD8+ T cells in brain, dLNs, peripheral LNs, and PB to validate the results." (PMID 36759517, 2023). "Subgroup 1 exhibited elevated expression levels of cell cycle genes PCNA and MKI67, as well as the tumor stem cell marker CD44." (PMID 37608794, 2023). "Previous studies have reported that a high level of CD44 expression enhances the defense against ROS in gastrointestinal cancer, and the deletion of CD44+ CSC populations suppresses tumor growth." (PMID 38201903, 2023). "Tumor cells greatly express this receptor as the CD44/HA interaction is indispensable for tumor invasion." (PMID 37283735, 2023). "As a biomarker for cancer, the level of CD44 present in the tumor cells has an essential role in cancer incursion, evolution, and metastasis." (PMID 37754116, 2023). "Regarding stem-cell characteristics, NEK8 knockdown decreased the tumour sphere formation, aldehyde dehydrogenase activity, and stem-cell marker expression, including that of CD44, Sox2, Oct4a, and Nanog." (PMID 37100815, 2023). "An important question concerns how tumor cells use the two different signaling pathways of HA binding to CD44 or integrins binding to their ligands." (PMID 37835592, 2023). "The interaction between HA and CD44 is crucial for activating CD44, which triggers tumorigenic signaling pathways involved in tumor development, metastasis, and chemo-resistance." (PMID 37509716, 2023).